ENSG00000254553 (novel transcript)
Gene: Protein-coding gene on chromosome 1 (32,465,057 to 32,600,792, forward strand). Ensembl gene ENSG00000254553.
Genetic constraint (gnomAD): Missense variants: 487 observed, 631.39 expected, observed/expected ratio (o/e) 0.77, 90% interval 0.71 to 0.83. Synonymous variants: 234 observed, 247.64 expected, observed/expected ratio (o/e) 0.94, 90% interval 0.85 to 1.05.